P2RY8 (P2Y receptor family member 8)
Description:
G protein-coupled receptor for S-geranylgeranyl-glutathione (GGG), an endogenous metabolite present in lymphoid tissues. Couples the binding of GGG to the activation of GNA13 and downstream repression of AKT activation in lymphocytes defining their positioning and growth within lymphoid organs. In lymphoid follicles, confines B cells and follicular helper T cells in germinal centers (GCs) in response to GGG local gradients established by GGT5 (via GGG catabolism) and ABCC1 (via extracellular transport) with lower concentrations of GGG found in the follicular dendritic cell network region around which germinal centers are formed. In the bone marrow, also in response to GGG gradients established by GGT5 and ABCC1, it restricts chemotactic transmigration of B cells, T cells and NK cells from blood vessels to the bone marrow parenchyma. Contributes to GNA13-dependent pathway that suppresses GC B cell growth.
Synonyms: P2Y8
Tractability: Small molecule: it belongs to a druggable protein family. Antibody: UniProt places it where antibodies can reach, with high confidence; its Gene Ontology location is reachable by antibodies, with high confidence; UniProt predicts a signal peptide or a membrane-spanning region. PROTAC: ubiquitination databases record sites on it; its protein half-life has been measured.
Target class: Purine receptor; Small molecule receptor (family A GPCR); Membrane receptor; Family A G protein-coupled receptor; Nucleotide-like receptor (family A GPCR)
Gene: Protein-coding gene on chromosome X (1,462,572 to 1,537,187, reverse strand). Ensembl gene ENSG00000182162.
Subcellular location: Cell membrane
Gene Ontology:
Molecular function: G protein-coupled receptor activity; protein binding; G protein-coupled purinergic nucleotide receptor activity
Biological process: Rho-activating G protein-coupled receptor signaling pathway; G protein-coupled receptor signaling pathway; G protein-coupled purinergic nucleotide receptor signaling pathway
Cellular component: plasma membrane; membrane
Homologues: Orthologues: chimpanzee P2RY8 (99% identical), macaque P2RY8 (94% identical), pig P2RY8 (81% identical), dog P2RY8 (78% identical), rabbit P2RY8 (75% identical), tropical clawed frog p2ry8 (52% identical), zebrafish p2ry8 (47% identical). Paralogues in human: F2RL1 (30% identical), F2R (30% identical), F2RL2 (27% identical), LPAR4 (27% identical), F2RL3 (26% identical), CYSLTR1 (24% identical), LPAR6 (24% identical), GPR17 (23% identical), P2RY10 (23% identical), GPR65 (22% identical), GPR20 (22% identical), CYSLTR2 (21% identical), and 4 more.
Diseases named in the same sentence as P2RY8 in open-access papers:
P2RY8 is named in the same sentence as 20 diseases in open-access papers, as found by Europe PMC text mining. Sharing a sentence is not in itself a finding about the gene and the disease. The quoted sentences say what the papers report.
leukemia (4 papers, 2014 to 2025). A malignant (clonal) hematologic disorder, involving hematopoietic stem cells and characterized by the presence of primitive or atypical myeloid or lymphoid cells in the bone marrow and the blood. "Additionally, P2RY8 has been found to be upregulated in leukemias and expression of P2RY8 in 3T3 cells resulted in their ability to form tumors in vivo, suggesting it may serve as a proto-oncogene." (PMID 27655702, 2016). "Thus, P2RY8 may be over-expressed simply by residing in a very active genomic region or it may play a functional role in transforming leukemia cell clones." (PMID 24959420, 2014).
lupus (3 papers, 2022 to 2024). "P2RY8 expression was additionally decreased in metabolically active cluster 9, which is intriguing given recent evidence that decreased B cell P2RY8 propagates pathogenic antibodies and ABCs in humans with lupus or antiphospholipid syndrome." (PMID 37129971, 2023). "Loss of P2RY8 is likely to disrupt B cell tolerance and contribute to lupus pathogenesis." (PMID 34889940, 2022). "Here, we describe the first novel, ultrarare (minor allele frequency [MAF] < 0.0001) and rare (MAF < 0.005) germline P2RY8 variants, identified in patients with SLE or lupus-related antiphospholipid syndrome (APS)." (PMID 34889940, 2022). "P2RY8 was downregulated in some B cell subsets of lupus patients, and low expression of P2RY8 correlated with nephritis and extrafollicular ABCs." (PMID 38866437, 2024). "To explore the hypothesis that P2RY8 expression promotes tolerance in developing B cells, we examined the effect of expressing P2RY8 in mice that also express the DNA-reactive VH3H9 heavy chain that is derived from a lupus-prone mouse strain." (PMID 34889940, 2022). "Moreover, a similar downregulation of P2RY8 in DN B cells (but not in T cells) was seen in AU non-Asian SLE patients with renal involvement, suggesting that P2RY8 downregulation can be extrapolated to non-Chinese SLE and appears to serve as a biomarker of renal lupus." (PMID 34889940, 2022).
glioma (1 paper, 2021). A benign or malignant brain and spinal cord tumor that arises from glial cells (astrocytes, oligodendrocytes, ependymal cells). "The results showed that TRIM38, CCR5, PLAU, P2RY8, and PROS1 have a higher immunoreaction score (IRS) in tumors than normal tissues (p < 0.05), while the IRS of HAMP and S100A9 in gliomas were lower than normal tissues (p < 0.05)." (PMID 34954691, 2021). "TRIM38, CCR5, PLAU, P2RY8, and PROS1 were upregulated in glioma tissues, while HAMP and S100A9 were downregulated." (PMID 34954691, 2021). "We observed that the IRSs of PROS1, P2RY8, PLAU, CHI3L2, MSR1, CCR5, and TRIM38 were higher than its corresponding IRSs in low-grade glioma, while the IRSs of HAMP, CARD16, and S100A8 in high-grade glioma were lower than low-grade glioma." (PMID 34954691, 2021).
lung carcinoma (1 paper, 2020). "Next, we determined the expression levels of P2X sub-families P2RX1–7 and P2Y receptors P2RY1, P2RY2, P2RY4, P2RY5 (LPAR6), P2RY6, P2RY7 (LTB4R), P2RY8, P2RY9 (LPAR4), P2RY10–14 in normal lung tissues and lung cancer tissues." (PMID 32638267, 2020).
lupus nephritis (1 paper, 2022). Glomerulonephritis in the context of systemic lupus erythematosus. "Downregulation of P2RY8 was more prominent in patients with lupus nephritis." (PMID 34889940, 2022).
lymphoid leukemia (1 paper, 2016). A malignant lymphocytic neoplasm of B-cell or T-cell lineage involving primarily the bone marrow and the peripheral blood. "Given that the regulatory element of P2RY8 is highly active in lymphoid cells, it is fitting that the P2RY8-CRLF2 rearrangement, which places the proto-oncogenic CRLF2 under control of the P2RY8 regulatory element, is correlated with lymphoid leukemia." (PMID 27655702, 2016).
cancer (5 papers, 2022 to 2025). A tumor composed of atypical neoplastic, often pleomorphic cells that invade other tissues. "Specifically, P2RY8, a recently de-orphanized receptor responding to the extracellular molecular S-geranylgeranyl-L-glutathione (GGG), exhibited a high positive correlation six cancer hallmark pathways related to cell survival, proliferation, immune evasion, and metastasis." (PMID 39766077, 2024). "SOX5 also regulates a variety of targets in cancers, including EZH2, twist 1, P2RY8, MITF, and others." (PMID 35880568, 2022).
tumor (4 papers, 2016 to 2021). "Here, we initially observed elevated levels of pro-inflammatory cytokines (most notably TNF), infiltration of inflammatory cells, and upregulation of four GPCR-associated genes (CCR10, P2RY8, ARRB1, and RGS10) in human HCC tumor and paracancerous specimens." (PMID 29445190, 2018). "However, the deletion leading to the fusion of P2RY8 and CRLF2 also results in the deletion of several genes (P2RY8, CSF2RA, IL3RA, SLC25A6, and ASMTL) whose potential roles as tumor suppressors should not be discounted." (PMID 27655702, 2016).
P2RY8 also shares sentences with these, for which no sentence is quoted: colorectal cancer (3 papers); antiphospholipid syndrome (2); lymphoma (2); nephritis (2); acute lymphoblastic leukemia (1); breast carcinoma (1); Burkitt lymphoma (1); cavernous hemangioma (1); diffuse large B-cell lymphoma (1); follicular lymphoma (1); hematological malignancies (1); osteosarcoma (1).